JAK2 (Janus kinase 2)
Diseases named in the same sentence as JAK2 in open-access papers (continued):
Sharing a sentence is not in itself a finding about the gene and the disease.
Sepsis (continued). "We further investigated the protective role of MF against SAT in a mouse model of cecal ligation and puncture (CLP)-induced sepsis, focusing on the JAK2/STAT3 signaling pathway in the liver." (PMID 37240208, 2023). "In the experimental models of sepsis, JAK2 inhibitors have been shown to block the classical p65RelA/p50 NFκB pathway, inhibiting the production of inflammatory factors, thus saving animals from sepsis." (PMID 37122731, 2023). "The inactivation of JAK2/STAT3 signaling pathway is a therapeutic target for sepsis through regulating inflammation." (PMID 37650558, 2023). "Coincidentally, a recent publication has shown that XBJ can improve sepsis-induced myocardial damage and inflammation by regulating the NF-κB and JAK2/STAT3 pathways." (PMID 38094883, 2023). "The JAK2/STAT3 signaling pathway mediates IL-6 during sepsis and delivers it to particular effector cells, which are ultimately destroyed." (PMID 37650558, 2023). "Piceatannol restored the impaired cardiac function by inhibiting the JAK2/STAT3 (Janus kinase 2/signal transducer and activator of transcription 3) pathway in cecal ligation and puncture‐induced septicemia animals and LPS‐stimulated H9c2 cardiomyocytes." (PMID 36655110, 2023). "In fact, IFNγ, whose receptor signals through JAK2, is believed to partially rescue the endotoxin tolerance phenotype in human monocytes, and IFNγ is sometimes used in sepsis treatment to improve immune host defense, perhaps activating JAK2 more intensively." (PMID 34867954, 2021). "The JAK2 inhibition can protect the animals from polymicrobial sepsis by modulating macrophage activation and cytokine production." (PMID 32641132, 2020). "JAK2 is an essential tyrosine kinase for modulating the immune response and whose activation contributes to the severe inflammatory response in sepsis." (PMID 27472318, 2016). "The JAK2 is an essential tyrosine kinase for modulating the immune response, which contributes to “early” inflammatory response in sepsis when phosphorylated at Tyr1007/1008." (PMID 23840548, 2013). "The present study, based on the mouse models of sepsis-induced acute lung injury, explored whether lidocaine exerts an anti-inflammatory effect by regulating the JAK2/STAT3 pathway and whether it can affect the apoptosis of lung cells." (PMID 40338919, 2025). "Studies have shown that JAK2 can be rapidly activated when sepsis occurs." (PMID 40338919, 2025). "Thus, effective suppression of the JAK2/STAT3 pathway appears to have substantial therapeutic value in sepsis and diseases with comparable pathogenesis." (PMID 39955435, 2025). "The aims of this study were to investigate whether TLR4/IKKα-mediated NF-κB and JAK2/STAT3 pathways were involved in XBJ's cardio-protection during sepsis and the mechanisms." (PMID 37650558, 2023). "Downregulation of Socs1 in rat hepatocytes activates Jak2-Stat3 in an animal model of sepsis." (PMID 36505769, 2022). "The increase in JAK2 protein during sepsis was significant only in OVR females." (PMID 35322092, 2022). "We then confirm the implication of the JAK2-STAT pathway in the aberrant DNA methylome of patients with sepsis caused by gram-negative bacteria." (PMID 34867954, 2021). "Inhibition of JAK2 prevents NF-κB activation; thus “rescuing” mice from polymicrobial sepsis." (PMID 27472318, 2016). "α7 nAChR agonists control systemic inflammation in sepsis by inhibiting the JAK2/STAT3 pathway which plays an important role in transducing a multitude of inflammatory signals; it has been considered as a therapeutic target for suppressing inflammatory process." (PMID 23840548, 2013). "Therefore, resisting apoptosis by inhibiting the activation of TLR4/NF-κB and JAK2/STAT3 signaling pathways may have clinical benefits for patients who suffer from sepsis induced myocardial dysfunction." (PMID 37650558, 2023).
Sepsis (continued). "However, it remains uncertain whether YTHDF2 affects HMGB1 release and whether the impact of YTHDF2 on HMGB1 release is connected to the regulation of the IL-6R/JAK2/STAT1 pathway in sepsis." (PMID 38026444, 2023). "The most severe and hyperinflammatory cases of sepsis-associated HLH could benefit from therapies that target cytokine storms, such as anakinra (anti-IL-1), tocilizumab (anti-IL-6), and/or ruxolitinib (anti-JAK2)." (PMID 34692727, 2021). "This suggests that JAK2 may serve as an upstream kinase of STAT3 during CLP-induced sepsis." (PMID 32943679, 2020). "Upon examination of our results, the expression and phosphorylation of the JAK2/STAT3 signaling pathway were significantly elevated in groups with a heavy inflammatory load, such as the sepsis and TCZ16 groups." (PMID 39955435, 2025). "miR-206 plays a role in modulating inflammation by regulating neutrophil recruitment in infections and alleviating inflammatory injury via the JAK2/STAT3 pathway, relevant in sepsis and other inflammatory conditions." (PMID 40621499, 2025). "Previous studies have shown that the activated JAK2/STAT3 signaling pathway can trigger the release of pro-inflammatory and pro-apoptotic proteins during sepsis." (PMID 37650558, 2023). "It is shown that the activation of TLR4/NF-κB and JAK2/STAT3 pathways induced apoptosis and inflammation during sepsis." (PMID 37650558, 2023). "Previous studies have shown that JAK2 and STAT3 are activated in an experimental mammalian sepsis model." (PMID 32641132, 2020). "In experimental studies, inhibition of JAK2 with AG490 or STAT3 with rapamycin attenuated organ damage and severe sepsis mortality." (PMID 28182798, 2017). "This case report describes a rare dual crisis: a 79 year old female patient who had not previously been diagnosed with JAK2 V617F mutation-associated ET but simultaneously developed acute STEMI and sepsis." (PMID 41560006, 2026). "In addition, SOCS3, a suppressor of the JAK2/STAT3 pathway, exhibited higher expression in the sepsis and TCZ16 groups, as anticipated, in response to high inflammation." (PMID 39955435, 2025). "In summary, these findings demonstrate that YTHDF2 plays an essential role as an inhibitor of inflammation to reduce the release of HMGB1 by inhibiting the IL-6R/JAK2/STAT1 pathway, indicating that YTHDF2 is a novel target for therapeutic interventions in sepsis." (PMID 38026444, 2023). "Our findings demonstrate that YTHDF2 plays an essential role as an inhibitor of inflammation by reducing the release of HMGB1 via inhibition of IL-6R/JAK2/STAT1 signalling, indicating that this pathway may be a novel therapeutic strategy for sepsis." (PMID 38026444, 2023). "Our results indicate that YTHDF2 plays an anti-inflammatory role by reducing the release of HMGB1 via inhibition of the IL-6R/JAK2/STAT1 pathway, demonstrating that targeting YTHDF2 may constitute a promising approach to sepsis treatment." (PMID 38026444, 2023). "In addition, methotrexate (MTX), an anti-inflammatory agent that inhibits the JAK2/STAT3 pathway, has been shown to ameliorate systemic inflammation and lung injury in a rat model of CLP sepsis." (PMID 35726235, 2022). "When activation of JAK2 and Src following sepsis was estimated by their phosphorylation in liver tissues, the phosphorylated levels of JAK2, but not of Src, were significantly increased 6–18 h after CLP." (PMID 32943679, 2020). "During sepsis, growth hormone (GH) resistance contributes to the catabolism of muscle protein suggesting that TNF mediates hepatic GH resistance during sepsis by inhibiting the duration of signaling via the Janus kinase-2/STAT5 pathway." (PMID 25147565, 2014). "Inhibition of JAK2 and STAT3 tyrosine phosphorylation may reduce TNF-α level in sepsis in vivo, indicating TNF-α is also involved in the JAK2/STAT3 pathway in anti-inflammation." (PMID 23840548, 2013).
Sepsis (continued). "Accumulating evidence suggests that the cross-talking of JAK2/STAT3 (p-JAK2 and phospho-Tyr705) with other pathways such as NF-κB (p-IKKα/β, p-IκBα and p-P65), MAPK (p-JNK, pJun, p-P38 and p-ERK1/2), AKT (p-AKT), TLR4, mediate hyperinflammatory factor production during sepsis." (PMID 41042728, 2025). "In addition, the JAK2/STAT3 pathway plays a role in the onset and progression of sepsis." (PMID 37650558, 2023). "Moreover, the JAK2/STAT3 and NF-κB signaling pathway might be involved in sepsis-induced AKI." (PMID 31084615, 2019).
Hodgkins lymphoma (36 papers, 2010 to 2025). A heterogeneous group of malignant lymphoid neoplasms of B-cell origin characterized histologically by the presence of Hodgkin and Reed-Sternberg (HRS) cells in the vast majority of cases. "SEC31A::JAK2 fusions are found in rare Hodgkin lymphoma cases and result in constitutive JAK2 activation." (PMID 40140631, 2025). "Dr. Shipp found that chromosome 9p24.1/PD-L1/PD-L2 alterations increase the abundance of the PD-L1 and PD-L2, and their further induction through Janus kinase 2 signal transducers and activators of transcription signaling in classical Hodgkin lymphomas." (PMID 36052227, 2022). "Patients with Hodgkin lymphoma often carry amplifications of the chromosome 9p24.1 locus containing PD‐L1, PD‐L2, and JAK2 genes, leading to high PD‐L1 and PD‐L2 protein expression." (PMID 35015307, 2022). "Amplification of chromosome 9p24.1 in Hodgkin lymphoma and B cell lymphoma was linked to PD-L1 upregulation and its neighbor gene JAK2 (Janus kinase 2), which also induced PD-L1 transcriptional activation." (PMID 34503236, 2021). "MiR-135a promotes the apoptosis of classical Hodgkin lymphoma by mediating downregulated expression of Janus kinase 2 (JAK2) and decreasing the anti-apoptotic gene Bcl-xl (BCL2L1) expression." (PMID 32710726, 2020). "For example in Hodgkin lymphoma, a high mutation rate in SOCS1 gene correlates with hyperactivation of JAK2 a gained PD-L1 expression." (PMID 29967604, 2018). "JAK 2 inhibition has proven efficient in vitro and in xenotransplant experiments and JAK2inhibition therefore is a reasonable approach in Hodgkin lymphoma." (PMID 29755699, 2018). "Fourth, JAK2 gene amplification cooccurrs with PD-L1 amplification in Hodgkin lymphoma and the amplified JAK2 gene dosage further increases PD-L1 expression." (PMID 29755699, 2018). "JAK2 amplification via telomeric segment translocation (9p24) leading to increased JAK2 expression and kinase activity has been described in Hodgkin lymphoma and primary mediastinal B-cell lymphoma." (PMID 29455667, 2018). "Van Roosbroeck found a SEC31A-JAK2 fusion in classical Hodgkin lymphoma and showed that SEC31A-JAK2 Ba/F3 transformed cells were sensitive to treatment with JAK2 inhibitors." (PMID 29262599, 2017). "In conclusion, JMJD2C and JAK2 cooperatively remodel the epigenome of Hodgkin lymphoma and primary mediastinal B-cell lymphoma, providing the possibility of the discovery of JAK2 and JMJD2C inhibitors for these malignant diseases." (PMID 29207681, 2017). "Classical Hodgkin lymphoma and primary mediastinal large B-cell lymphoma with 9p24.1/JAK2 copy gain(s) were sensitive to treatment with the JAK2-selective inhibitor fedratinib both in vitro and in vivo." (PMID 29262599, 2017). "In contrast, this miRNA is also considered to be a tumor suppressor in Hodgkin lymphoma by inhibition of JAK2 expression thereby favoring apoptosis (Lawrie, 2012)." (PMID 28560185, 2017). "In classic Hodgkin lymphoma, miR-135a mediates Janus kinase 2 (JAK2) downregulation and decreases both the mRNA and protein levels of the anti-apoptotic gene Bcl-xL (BCL2L1), leading to apoptosis." (PMID 27486383, 2016). "Of interest, PD-L1, PD-L2 and JAK2 amplification is a characteristic of Hodgkin lymphoma, which is exquisitely sensitive to nivolumab." (PMID 27942391, 2016). "Mutations in SOCS1 have previously been shown to stabilize p(hospho-) JAK2 in primary mediastinal B- cell lymphoma and boost pSTAT5 stockpiling in Hodgkin lymphoma." (PMID 27144517, 2016). "It was also previously report to regulate JAK2 and promote a favorable outcome in classic Hodgkin lymphoma." (PMID 25646775, 2015). "Additionally, in the classical Hodgkin lymphoma and the primary mediastinal large B-cell lymphoma, the amplified region of the 9p24.1 chromosome also includes the Janus kinase 2 (JAK2) locus." (PMID 38762484, 2024).
Hodgkins lymphoma (continued). "Furthermore, in Hodgkin lymphoma, chromosomal abnormalities of 9p24.1,a genomic region that includes CD274, PDCD1LG2 (encoding PD-L), and Janus kinase 2(JAK2), have been correlated with increased PD-L1 expression." (PMID 26361042, 2015). "Fortunately, some target drugs gene therapy have been reported, such as JAK2 selective inhibitor, basing on disease-specific chromosome 9p24.1/JAK2 amplification increased JAK2 expression and activity in bothprimary mediastinal large B-cell lymphoma and Hodgkin lymphoma." (PMID 26715530, 2015). "Amplification of chromosome 9p24.1, which contains PD-L1, PD-L2, and Janus kinase 2 (JAK2), is commonly found in Hodgkin’s lymphoma, triple-negative breast cancer (TNBC), and NSCLC." (PMID 37877810, 2024). "The effects of miR-135a on the JAK2/STAT5 pathway lead to apoptosis and survival of classical Hodgkin lymphoma." (PMID 32710726, 2020). "JMJD2C was considered as an oncogene due to its firstly discovered in primary Hodgkin lymphoma and mediastinal B-cell lymphoma, in which both of JMJD2C and tyrosine kinase JAK2 (Janus kinase 2) were found to have the function of epigenetic regulation." (PMID 29207681, 2017). "SOCS1 inactivating mutations or deletions have been previously shown to abolish control of phospho-JAK2 or phospho-STAT5 signaling in primary mediastinal B-cell and Hodgkin lymphomas, recalling the picture described here for JAK3 and SOCS1." (PMID 27144517, 2016). "The Hodgkin lymphoma cell line HDLM-2 has been demonstrated to show constitutive phosphorylation of JAK1 and JAK2, and STAT1, STAT3, STAT5 and STAT6." (PMID 26131691, 2015). "Hodgkin's lymphoma L540 cells had high levels of phospho-JAK3 but undetectable levels of phospho-JAK1 and -JAK2." (PMID 20149240, 2010). "JAK1, JAK2, and JAK3 immunoprecipitates were prepared from the lysates of Hodgkin's lymphoma HDLM-2 or L540 cells, where persistently-active JAK1 and JAK2 or JAK3 are expressed, respectively." (PMID 20149240, 2010). "Aberrant STAT3 activation has been documented in MM, Hodgkin's disease, anaplastic lymphoma kinase-positive (ALK) DLBCL, and activated B-cell (ABC) DLBCL, in which JAK2/STAT3 inhibitors trigger arrest and apoptosis." (PMID 20433747, 2010). "It acts as a causative factor for autocrine and paracrine activation of canonical and noncanonical NF-κB signaling as well as promotes JAK2/STAT6 signaling in Hodgkin lymphoma resulting in prevention of apoptosis." (PMID 40186177, 2025). "The third mechanism has been described in Hodgkin lymphomas (classical Hodgkin lymphomas and nodular lymphocyte-predominant Hodgkin lymphomas) and PMBL, in which both high JAK2 expression and p-STAT6 were observed and attributed to SOCS1 mutations via the disruption of a negative feedback loop." (PMID 37835560, 2023).
myocardial infarction (36 papers, 2007 to 2026). Gross necrosis of the myocardium, as a result of interruption of the blood supply to the area, as in coronary thrombosis. "As an example, in oxygen-glucose deprivation-induced cardiomyocyte injury, lncRNA MIAT, which is associated with myocardial infarction, captures miR-181a-5p and boosts the expression of JAK2." (PMID 38495094, 2024). "In young adults, JAK2 variants nearly quadruple the risk of myocardial infarction." (PMID 39194713, 2024). "Long non-coding RNA myocardial infarction-associated transcript (LncRNA MIAT) sponged miR-181a-5p to enhance the expression of JAK2 and thus increased the JAK2/STAT3 signaling pathway to induce inflammation and apoptosis in oxygen-glucose deprivation-induced cardiomyocyte." (PMID 36148063, 2022). "This research highlights key genes associated with mitochondrial oxidative stress—VCL, ABCB1, JAK2, KDR, NGF—that show differential expression in DCM and myocardial infarction." (PMID 40217309, 2025). "Inhibiting JAK2/STAT3 phosphorylation reduces malignant ventricular arrhythmias post-myocardial infarction by attenuating ventricular remodeling." (PMID 38495094, 2024). "MT reduced myocardial infarction size by activating the JAK2/STAT3 pathway and upregulating HSP70 expression." (PMID 39041001, 2024). "Previous research demonstrated that cardiomyocyte apoptosis caused by acute myocardial infarction resulted in a decrease in the bcl-2/bax ratio and expression of p-JAK2 and p-STAT3, while the expression of p-JAK2 and p-STAT3 protein increased significantly." (PMID 37567042, 2023). "In the LAD ligation of a rat model, as early as 5 minutes after myocardial infarction, we observed JAK2, STAT1, STAT3, STAT5a, and STAT6 phosphorylation." (PMID 34516361, 2021). "Rapamycin reduces myocardial infarction in the diabetic mice heart via inhibiting mTOR thus activating the Janus kinase 2 (JAK2) /signal transducer and activator of transcription 3 (STAT3) signaling pathway." (PMID 30705773, 2019). "On the other hand, a study suggested that LINC00664/hsa-miR-197-3p/JAK2 interaction may be a biomarker for life-threatening myocardial fibrosis after acute myocardial infarction." (PMID 41009512, 2025). "The association with JAK 2 variants is particularly concerning, as it poses a maximum risk for coronary syndrome, as evidence shows that this scenario counts for 20% of the patients with CHIP and myocardial infarction." (PMID 39194713, 2024). "JAK2 has been associated with the copresence of CHIP and myocardial infarction." (PMID 35872888, 2022). "It is reported that NR4A3 overexpression could increase the activity of JAK2/STAT3 signaling in the heart of mice after myocardial infarction and alleviate the inflammatory response after myocardial infarction." (PMID 35747513, 2022). "G-CSF can prevent ventricular remodeling after acute myocardial infarction and improve myocardial ischemia, which may be ascribed to direct activation of the Jak2/STAT3 pathway and promotion of local revascularization." (PMID 33817262, 2020). "Moreover, O3 also activated the JAK2/STAT3 signaling, upregulated the expression of HSP70 both in vitro and vivo, and decreased the index of apoptosis of cardiomyocytes caused by I/R as well as myocardial infarct area in vivo." (PMID 34516361, 2021). "Thirdly, inflammatory signaling: In myocardial infarction models, TMAO activates JAK2-STAT3 in cardiac fibroblasts, increasing JAK2/STAT3 phosphorylation and fibronectin/collagen I/III synthesis." (PMID 41277967, 2025). "D. salina extract treatment (0.1 mg/kg) was able to decrease myocardial infarct size and attenuate the expressions of cyclooxygenase-2 (COX-2) and the activity of STAT1, janus kinase 2 (JAK2), inhibitor of IκB, NF-κB." (PMID 38786620, 2024).
myocardial infarction (continued). "Relevant studies have shown the JAK2/STAT3 pathway is involved in the signal transduction process of cardiac hyperplasia and hypertrophy induced by various factors, and its activation is observed in myocardial infarction and dilated cardiomyopathy." (PMID 35609321, 2022). "The mechanism may be related to the increase in the expression of p-JAK2 and p-STAT3 after S-post, which led to reduced mitochondrial ROS generation and increased mitochondrial ATP content, thereby reducing apoptosis and myocardial infarct size." (PMID 28392989, 2017). "The mechanism may be related to an increased expression of p-JAK2 and p-STAT3 after S-post, which reduced mitochondrial ROS generation and increased mitochondrial ATP content, thereby reducing apoptosis and myocardial infarct size." (PMID 28392989, 2017). "The mechanism may be related to an increased the expression of p-JAK2 and p-STAT3 after S-post, which lead to reduced mitochondrial ROS generation and increased mitochondrial ATP content, thereby reducing apoptosis and myocardial infarct size." (PMID 28392989, 2017).